RABGGTA (Rab geranylgeranyltransferase subunit alpha)
Description:
Catalyzes the transfer of a geranylgeranyl moiety from geranylgeranyl diphosphate to both cysteines of Rab proteins with the C-terminal sequence -XXCC, -XCXC and -CCXX, such as RAB1A, RAB3A, RAB5A and RAB7A.
Synonyms: PTAR3
Tractability: Small molecule: a high-quality ligand is known. Antibody: its Gene Ontology location is reachable by antibodies, with high confidence. PROTAC: ubiquitination databases record sites on it; its protein half-life has been measured; a small molecule that binds it is known.
Target class: Enzyme; Transferase
Gene: Protein-coding gene on chromosome 14 (24,265,538 to 24,271,611, reverse strand). Ensembl gene ENSG00000100949.
Pathways (Reactome):
Metabolism of proteins: RAB geranylgeranylation
Gene Ontology:
Molecular function: protein binding; protein geranylgeranyltransferase activity; Rab geranylgeranyltransferase activity; small GTPase binding; protein prenyltransferase activity; zinc ion binding
Biological process: endoplasmic reticulum to Golgi vesicle-mediated transport; protein geranylgeranylation; protein modification process; visual perception
Cellular component: cytosol; plasma membrane; Rab-protein geranylgeranyltransferase complex; cytoplasm
Genetic constraint (gnomAD): Loss-of-function variants: 69 observed, 84.3 expected, observed/expected ratio (o/e) 0.82, 90% interval 0.67 to 1. The upper end of that interval is the gene's LOEUF score, 1, which puts it in group 4 of 6, group 1 being the genes least tolerant of losing a copy. Missense variants: 680 observed, 721.78 expected, observed/expected ratio (o/e) 0.94, 90% interval 0.88 to 1. Synonymous variants: 310 observed, 302.3 expected, observed/expected ratio (o/e) 1.03, 90% interval 0.93 to 1.13.
Homologues: Orthologues: chimpanzee RABGGTA (99% identical), pig RABGGTA (95% identical), dog RABGGTA (94% identical), rabbit RABGGTA (93% identical), guinea pig RABGGTA (92% identical), rat Rabggta (91% identical), mouse Rabggta (91% identical), macaque RABGGTA (87% identical), tropical clawed frog rabggta (60% identical), zebrafish rabggta (57% identical), Caenorhabditis elegans M57.2 (32% identical), Drosophila melanogaster RabGGTa (31% identical). Paralogues in human: FNTA (14% identical), PTAR1 (13% identical).
Diseases named in the same sentence as RABGGTA in open-access papers:
RABGGTA is named in the same sentence as 4 diseases in open-access papers, as found by Europe PMC text mining. Sharing a sentence is not in itself a finding about the gene and the disease. The quoted sentences say what the papers report.
schizophrenia (2 papers, 2020). A major psychotic disorder characterized by abnormalities in the perception or expression of reality. "To test this, we assayed protein expression of the five prenyltransferase subunits (FNTA, FNTB, PGGT1B, RABGGTA, and RABGGTB) in postmortem dorsolateral prefrontal cortex from patients with schizophrenia and paired comparison subjects (n = 13 pairs)." (PMID 32066669, 2020). "Accordingly, we assayed protein expression of the prenyltransferases subunits FNTA, FNTB, PGGT1B, RABGGTA, and RABGGTB in DLPFC from schizophrenia and matched comparison subjects." (PMID 32066669, 2020).
Insulin resistance (1 paper, 2022). Increased resistance towards insulin, that is, diminished effectiveness of insulin in reducing blood glucose levels. "Consistently, RABGGTA knockdown‐mediated GGTase II inhibition in skeletal muscle caused insulin resistance without disturbing insulin signalling in vivo." (PMID 35961942, 2022).
cancer (3 papers, 2016 to 2026). A tumor composed of atypical neoplastic, often pleomorphic cells that invade other tissues. "As RabGGTase is a good target for cancer therapy, the effects of specific inhibitors of RabGGTA are under investigation; these inhibitors may represent a novel approach for cancer therapy." (PMID 27462771, 2016). "Several candidates identified in our experiment, either in CuCl2-or CuCl2 and LA-treated groups, are directly involved in cancerogenesis (such as MEMO1, ATOX1, L1CAM, RABGGTA, MAP2K7 and others, and may be of potential interest for anti-cancer research." (PMID 39290994, 2024).
RABGGTA also shares sentences with these, for which no sentence is quoted: leiomyoma (1 paper).